EPHX3 (epoxide hydrolase 3)
Description:
Catalyzes the hydrolysis of epoxide-containing fatty acids. Active in vitro against epoxyeicosatrienoic acids (EETs) including 8,9-EET, 9,10-EET, 11,12-EET and 14,15-EET and leukotoxin.
Synonyms: EH3; ABHD9; FLJ22408
Tractability: Antibody: UniProt predicts a signal peptide or a membrane-spanning region.
Gene: Protein-coding gene on chromosome 19 (15,226,899 to 15,233,591, reverse strand). Ensembl gene ENSG00000105131.
Subcellular location: Microsome membrane
Subcellular location (Human Protein Atlas): Nucleoplasm
Gene Ontology:
Molecular function: epoxide hydrolase activity; catalytic activity
Biological process: epoxide metabolic process
Cellular component: intracellular membrane-bounded organelle; membrane
Genetic constraint (gnomAD): Loss-of-function variants: 37 observed, 41.75 expected, observed/expected ratio (o/e) 0.89, 90% interval 0.68 to 1.17. The upper end of that interval is the gene's LOEUF score, 1.17, which puts it in group 5 of 6, group 1 being the genes least tolerant of losing a copy. Missense variants: 441 observed, 465.55 expected, observed/expected ratio (o/e) 0.95, 90% interval 0.88 to 1.02. Synonymous variants: 209 observed, 205.32 expected, observed/expected ratio (o/e) 1.02, 90% interval 0.91 to 1.14.
Homologues: Orthologues: chimpanzee EPHX3 (99% identical), macaque EPHX3 (96% identical), pig EPHX3 (89% identical), dog EPHX3 (88% identical), mouse Ephx3 (83% identical), rat Ephx3 (80% identical), rabbit EPHX3 (74% identical), guinea pig EPHX3 (68% identical), Caenorhabditis elegans ceeh-2 (28% identical), zebrafish si:dkey-122a22.2 (13% identical), Drosophila melanogaster CG15879 (12% identical), Caenorhabditis elegans F10D2.10 (11% identical), and 11 more. Paralogues in human: EPHX4 (44% identical), EPHX2 (29% identical), ABHD8 (19% identical), ABHD5 (18% identical), SERHL2 (16% identical), ABHD11 (16% identical), BPHL (15% identical), ABHD6 (15% identical), MEST (15% identical), ABHD4 (14% identical), ABHD14A (12% identical), ABHD14B (11% identical).
Diseases named in the same sentence as EPHX3 in open-access papers:
EPHX3 is named in the same sentence as 29 diseases in open-access papers, as found by Europe PMC text mining. Sharing a sentence is not in itself a finding about the gene and the disease. The quoted sentences say what the papers report.
prostate carcinoma (5 papers, 2017 to 2022). A carcinoma that arises from epithelial cells of the prostate gland. "EPHX3 expression has been associated with increased risk of some malignancies, such as gastric cancer, melanoma, and prostate cancer." (PMID 35401746, 2022). "Studies have shown that patients with low EPHX3 expression in prostate cancer are more likely to relapse in their prognosis." (PMID 35401746, 2022).
adenoid cystic carcinoma (2 papers, 2019 to 2022). A malignant tumor arising from the epithelial cells. "A study by Bell (2011) used microarray analysis in patients with salivary gland adenoid cystic carcinoma for aberrant DNA methylation, and the results suggested that aberrant DNA methylation of EPHX3 is associated with adenoid cystic carcinoma development and progression." (PMID 31131446, 2019). "In addition, the downregulation of EPHX3 is related to the occurrence and development of adenoid cystic carcinoma of salivary gland." (PMID 35401746, 2022).
head and neck cancer (2 papers, 2021 to 2024). A primary or metastatic malignant neoplasm affecting the head and neck. "Head and neck cancer subjects with high EPHX3 expression have higher median survival (5.7 years) compared with subjects with low EPHX3 expression (2.1 years)." (PMID 33334892, 2021). "EPHX3 methylation was proposed as a prognostic marker for head and neck cancer." (PMID 38674360, 2024).
ichthyosis (2 papers, 2017 to 2021). Disorders of cornification that are characterized by visible scaling and/or hyperkeratosis of most or all of the skin. "The implication that EPHX3 expression could be associated with ichthyosis suggested it is involved in skin barrier function." (PMID 33334892, 2021). "Mouse gene knockout of SDR9C7 is neonatal lethal, as typical of ichthyosis-related genes, whereas, as noted, EPHX3 gene deficiency showed no overt phenotype." (PMID 33334892, 2021). "A previous study suggested that EPHX3 may be a candidate gene for ichthyosis, a debilitting skin condition." (PMID 28384353, 2017). "EpOMEs and DiHOMEs are abundant in the skin where altered metabolism may contribute to conditions such as ichthyosis or psoriasis; however, the murine knockout of EPHX3 did not alter the levels or metabolism of LA- or AA-derived epoxy fatty acids (EpFAs) in vivo and displayed no overt phenotype." (PMID 33334892, 2021).
salivary gland adenoid cystic carcinoma (2 papers, 2017 to 2022). An adenoid cystic carcinoma arising from the salivary gland. "The hypermethylation of EPHX3 was associated with salivary gland adenoid cystic carcinoma development and progression." (PMID 35846149, 2022).
atopic dermatitis (1 paper, 2019). "We assumed that the increase of trihydroxy-linoleic acids in atopic dermatitis patients is due to the increased gene expression of enzymes involved in CLE formation, ALOX12B (12R-LOX), ALOXE3 (eLOX3), and ABHD9 (EPHX3)." (PMID 30608955, 2019).
cardiac ischemia (1 paper, 2017). "Therefore, we challenged Ephx3-/- mice with cardiac ischemia/reperfusion injury and LPS-induced lung inflammation, which are both regulated by EETs." (PMID 28384353, 2017). "Overall, neither cardiac ischemia-injury nor LPS-induced inflammation unmasked phenotypes in the Ephx3-/- mice." (PMID 28384353, 2017).
head and neck squamous cell carcinoma (1 paper, 2022). A squamous cell carcinoma that arises from any of the following anatomic sites: lip and oral cavity, nasal cavity, paranasal sinuses, pharynx, larynx, and salivary glands. "The aim of this study was to explore the regulatory role of epoxide hydrolase 3 (EPHX3) in head and neck squamous cell carcinoma (HNSCC) and to analyze its bioinformatic function, as well as, to screen and predict the miRNAs that can regulate EPHX3 expression in HNSCC." (PMID 35401746, 2022).
ischemia (1 paper, 2017). A hypoperfusion of the BLOOD through an organ or tissue caused by a PATHOLOGIC CONSTRICTION or obstruction of its BLOOD VESSELS, or an absence of BLOOD CIRCULATION. "Hearts isolated from WT and Ephx3-/- mice were subjected to global no-flow ischemia followed by 40 minutes of reperfusion." (PMID 28384353, 2017).
melanoma (1 paper, 2017). A malignant, usually aggressive tumor composed of atypical, neoplastic melanocytes. "DNA methylation changes linked to melanoma progression on the examined candidates retained significance in the independent validation cohort (EPHX3 was not tested in this validation cohort)." (PMID 28578692, 2017).
nasopharyngeal carcinoma (1 paper, 2022). A carcinoma arising from the nasopharyngeal epithelium. "In data analysis and cell experiments, we have confirmed the low expression of EPHX3 in nasopharyngeal carcinoma cells, suggesting that EPHX3 may play an important role in nasopharyngeal carcinoma." (PMID 35401746, 2022).
Oral Squamous Cell Carcinoma (1 paper, 2022). "In Oral Squamous Cell Carcinoma, EPHX3 is closely related to lymph node involvement and secondary tumor events." (PMID 35401746, 2022).
tumor (7 papers, 2014 to 2022). "High expression of EPHX3 increases ceramide linoleate epoxide hydrolysis and functions to control flux through the alternative and crucial route of metabolism by the dehydrogenation pathway of SDR9C7, which implicated a role for EPHX3 in tumor suppression." (PMID 35846149, 2022). "Next, considering the potential tumor suppressor role of EPHX3 in HNSCC, we examined the association between EPHX3 and CD274, IL1B, IL1A, PDCD1, and PDCD1LG2." (PMID 35401746, 2022). "Together, our findings indicate that EPHX3 exerts its anticancer effects by suppressing tumor immune checkpoint expression and immune cell infiltration." (PMID 35401746, 2022). "While EPHX3’s enzymatic activities are poorly understood, several studies suggest that EPHX3 plays an important role in tumor suppression." (PMID 33334892, 2021). "Patients with hypomethylation of PAX9, STK33, GPR150, INSM1, and EPHX3 showed a shorter survival time and a higher tumor‐related mortality." (PMID 31131446, 2019). "Our data also show that EPHX3 may exert its anticancer effects by reducing tumor immune cell infiltration and immune checkpoint expression." (PMID 35401746, 2022). "Whether EPHX3 metabolism of linoleic epoxyalcohols confers protection against tumor progression remains to be determined." (PMID 33334892, 2021). "To further investigate the role of EPHX3 in tumor immunity, we used GEPIA to determine if there is a link between EPHX3 and the expression of immune cell biomarkers in HNSCC." (PMID 35401746, 2022). "Overall, our data uncovered miRNA-mediated EPHX3 downregulation as a contributor to poor HNSCC prognosis and reduced tumor immune infiltration." (PMID 35401746, 2022).
cancer (5 papers, 2017 to 2024). A tumor composed of atypical neoplastic, often pleomorphic cells that invade other tissues. "Here, we investigated EPHX3 expression levels and association with survival in various human cancers." (PMID 35401746, 2022). "Next, we examined the association between EPHX3 expression and survival in the 13 cancers." (PMID 35401746, 2022). "Notably, EPHX3 hypermethylation has been associated with the development of certain cancers." (PMID 38674360, 2024). "Among them, 8 of 12 hub genes (EPHX3, SPINK7, FCRLA, MASP1, ZNF541, CD5, BEST2, ZAP70) seemed to be cancer-promoting genes as they were downregulated in the high-risk group." (PMID 35846149, 2022). "The results of data analysis after TGCA showed that EPHX3 is a key regulator of tumorigenesis in 13 cancers and can be used as a marker of poor prognosis in HNSCC patients." (PMID 35401746, 2022). "Studies on gastric and prostate cancer have shown that decreased EPHX3 expression promotes cancer recurrence while lowering patient survival." (PMID 35401746, 2022). "To determine EPHX3 expression in various cancers, we carried out a pan-cancer analysis of EPHX3 expression on TCGA and GETX datasets." (PMID 35401746, 2022). "Moreover, several studies showed that CpG islands in the promoter of Ephx3 are methylated in various cancer cell lines." (PMID 28384353, 2017). "However, high EPHX3 expression only correlated significantly with better disease free survival (DFS) in HNSCC patients but not in other cancer types." (PMID 35401746, 2022).
renal disease (1 paper, 2020). "In our study, the progression of renal disease was consistent with the association between CN and activated Ephx3, leading to an increase in EpOME as a protoxin and an increase in its metabolite, DiHOME." (PMID 32344531, 2020).
EPHX3 also shares sentences with these, for which no sentence is quoted: acute respiratory distress syndrome (1 paper); breast carcinoma (1); cervix cancer (1); colon cancer (1); colorectal cancer (1); Ewing sarcoma (1); gastric cancer (1); hearing loss (1); hepatocellular carcinoma (1); infection (1); oral cancer (1); ovarian carcinoma (1); rectal cancer (1); skin disorder (1).